DMD (dystrophin)
Diseases named in the same sentence as DMD in open-access papers (continued):
Sharing a sentence is not in itself a finding about the gene and the disease.
dystrophinopathy (continued). "For this reason, it is not easy to decide whether the disease is a dystrophinopathy with defective expressions of SGCs or a LGMD with defective expression of dystrophin." (PMID 25050186, 2014). "Similar to earlier studies, we were not able to demonstrate a relationship between dystrophin levels and age, nor between dystrophin and the rate of decline in muscle force or function, although there may be a threshold that is relevant to the dystrophinopathy phenotype." (PMID 33723284, 2021). "All patients showed absent or decreased expression of dystrophin on immunohistochemical staining, proving the effectiveness of NGS combined with MLPA in the diagnoses of dystrophinopathies." (PMID 28403181, 2017). "In addition to dystrophin deficiency-induced cardiac fibrosis, calcium transients, and elevated ROS, ECG abnormalities may be secondary to dysregulated sodium, calcium, and potassium channels, kinases, and nitric oxide synthase (nNOS) triggered by the absence of dystrophin." (PMID 39056750, 2024). "However, in the patient described in this report, dystrophinopathies, such as DMD and BMD, were ruled out because the expression of sarcolemmal dystrophin was diffusely present and molecular tests for dystrophin gene were normal." (PMID 25050186, 2014).
cardiomyopathy (151 papers, 2009 to 2026). A disease of the heart muscle or myocardium proper. "By day 14 post-bioprinting, DMD-bCOs showed increased cell death and dysregulated expression of cardiac and fibrotic markers, mimicking DMD-associated cardiomyopathy." (PMID 41677066, 2026). "We report a case of adolescent-onset FSGS with ACTN4 mutation diagnosed during ACEi therapy for the prevention of DMD-associated cardiomyopathy." (PMID 41013435, 2025). "In the case of asymptomatic carriers’ family members, as the mother, it is important to arrange a cardiology consult, since heterozygotes for DMD have an increased risk for cardiomyopathy." (PMID 41583306, 2025). "Competency in medical knowledge: DMD-associated cardiomyopathy remains a poorly understood and undertreated aspect of the disease, despite being a leading cause of morbidity and mortality." (PMID 40724839, 2025). "For example, DMD is caused by mutations in the dystrophin gene that lead to severe neuromuscular dysfunction and fatal arrhythmias and cardiomyopathy." (PMID 39626239, 2025). "Cardiomyopathies due to dystrophin (DMD) variants classically mimic a posterior, inferior, and/or lateral myocardial infarction, with abnormal Q waves in leads I, aVL, and V6, or in leads II, III, and aVF, together with high-voltage R waves in leads V1 and V2." (PMID 40710800, 2025). "For modelling of DMD-associated cardiomyopathy, we prepared three pairs of isogenic control and dystrophin-deficient human induced pluripotent stem cell (hiPSC) lines." (PMID 38078368, 2024). "Several identified studies focused on the genotype–phenotype association with dystrophin-deficient cardiomyopathy." (PMID 39342355, 2024). "This blockade strategy offers promising therapeutic targeting in dystrophin-deficient cardiomyopathy as, in cardiac fibroblasts, AngII was further found to increase periostin expression via Ras/p38 MAPK/CREB and ERK1/2/Tgf-β1 pathways." (PMID 38255321, 2024). "It reveals several similarities with ECG abnormalities found in DMD patients, and reinforces the interest of the GRMD dog as a model for dystrophin-deficient cardiomyopathy." (PMID 38637619, 2024). "In the heart, GR deletion acted additively with dystrophin loss to exacerbate cardiomyopathy, resulting in enlarged hearts, pathological gene expression and systolic dysfunction, consistent with imbalanced mineralocorticoid signaling." (PMID 38770680, 2024). "This underscores the need to understand how dystrophin mutations cause cardiomyopathy beyond membrane instability alone." (PMID 39056750, 2024). "So far, the etiology of cardiomyopathy in female carriers with DMD mutation is still under elucidated, and studies are needed to identify the best diagnostic and therapeutic strategies for affected female." (PMID 38303044, 2024). "Previous research has shown that dystrophin-deficient mice with an infection exhibit more severe cardiomyopathy relative to mice with normal dystrophin." (PMID 39290213, 2024). "These GRMD dogs were compared to healthy control dogs to reveal alterations in LV myocardial strain during the pathological development of dystrophin-deficient cardiomyopathy." (PMID 37233184, 2023). "The presence of cardiomyopathy, closely related to the type of dystrophin gene mutation, strongly influences the life expectancy." (PMID 36672955, 2023). "It is due to a mutation in the DMD gene and causes muscular degeneration in conjunction with several secondary co-morbidities, such cardiomyopathy and respiratory failure." (PMID 36834757, 2023). "As a result, special care should be taken when modeling cardiomyopathies caused by gene mutations that impact calcium transients, such as DMD." (PMID 36290499, 2022). "In this study, BLITZ revealed several putative cavin interactors that have also been shown to be involved in cardiomyopathies and/or skeletal myopathies, including the membrane protein Dystrophin, the triad-associated proteins Bin1, Cypher/ZASP, and SPEG." (PMID 33591275, 2021).
cardiomyopathy (continued). "A filtering gene strategy revealed a co-segregated novel in-frame mutation (c.4998_5000 del CAG, p.1667 del Ala) in the dystrophin (DMD) gene which was associated with cardiomyopathies and fibro fatty replacement of cardiomyocytes in the left ventricle (LV)." (PMID 33567613, 2021). "Cardiomyopathy mouse model of dystrophin-deficient; Cardiac injury in murine model during ischemia-reperfusion." (PMID 34858991, 2021). "Sarcoglycan genes are associated with dystrophin and cardiomyopathies, including SGCA which encodes α component and was reported in relation to mild cardiomyopathies in the α-sarcoglycan-deficient mouse model." (PMID 33567613, 2021). "Dilated cardiomyopathy, ultimately leading to heart failure, is the most common outcome in patients with dystrophin mutations, and it develops in DMD patients due to muscle wasting, but remains mostly unexplained in its dynamics." (PMID 32656189, 2020). "Why is dystrophin-associated cardiomyopathy more widely studied in vitro compared to other forms of DCM?" (PMID 32477154, 2020). "The purpose of this article is to convey the realities of employing precision disease models of dystrophin-associated cardiomyopathy." (PMID 32977524, 2020). "Novel-15-3p, highly expressed in the Weddell seal heart, is associated with cardiomyopathy through its target dystrophin." (PMID 32293246, 2020). "Despite its low prevalence (<3/10,000), dystrophin-associated cardiomyopathy is the form of DCM that has been modeled in vitro more extensively using induced pluripotent stem cell-derived cardiomyocytes (iPSC-CMs) from patients." (PMID 32477154, 2020). "Women who are carriers of the DMD gene are largely asymptomatic with regard to skeletal muscle symptoms, but are susceptible to cardiomyopathy." (PMID 32636760, 2020). "Currently, none of the stem cell-based studies have reported or suggested novel pharmacological approaches for dystrophin-associated cardiomyopathies." (PMID 32477154, 2020). "From the clinical perspective, dystrophin-associated cardiomyopathy is characterized by a consistently severe phenotype, and progresses relentlessly." (PMID 32477154, 2020). "Through our work, we have showed that, despite sharing the common role of actin-binding and crosslinking proteins, ACTN2, FLNC and DMD mutations can cause different types of cardiomyopathies, ranging from HCM to RCM." (PMID 32824180, 2020). "For the first time, in this study, we provide evidence that exosome treatment stimulates cardioprotective signaling pathways in an in vitro model of dystrophin-deficient cardiomyopathy." (PMID 30410044, 2018). "Understanding how endogenous exosomes are changing the phenotype of the dystrophin-deficient cardiomyocyte will give greater understanding of the mechanisms of dystrophin-deficient cardiomyopathy." (PMID 30410044, 2018). "A recent review highlighted that both cardiac troponin T and dystrophin mutations play a role in cardiomyopathies in both humans and animals." (PMID 29367539, 2017). "In DD-MD the lack of functional dystrophin protein causes advancing muscle weakness, respiratory problems, and cardiomyopathy." (PMID 26401335, 2015). "The location of mutation/deletion within the dystrophin gene correlates with the severity of cardiomyopathy." (PMID 25988613, 2015). "As in Duchenne, X-linked and Becker muscular dystrophy, dystrophin degradation leads to cardiomyopathy." (PMID 25405382, 2015). "Disruption of the dystrophin complex has also been implicated in acquired forms of dilated cardiomyopathy and in cardiomyopathy occurring as a result of viral infection." (PMID 25405382, 2015). "Associations between specific dystrophin mutations and the severity of skeletal involvement as well as onset of cardiomyopathy have been reported." (PMID 25315351, 2014).
cardiomyopathy (continued). "Many of these genes encode proteins that work in association with dystrophin and/or are connected to muscle regeneration, and several others are affiliated with cardiomyopathy such as that observed in conjunction with DMD and GRMD." (PMID 24403852, 2013). "Mutations affecting the expression of dystrophin result in progressive loss of skeletal muscle function and cardiomyopathy leading to early mortality." (PMID 22937058, 2012). "This study shows significantly decreased relative radial strain at 9 and 12 months of age in the anterior mid wall of the left ventricular of dystrophin deficient mice with evidence of mild cardiomyopathy and myocardial fibrosis." (PMID 22307449, 2011). "In this study, high frequency based STI was used in the dystrophin deficient mdx mouse model both pre- and post-development of mild cardiomyopathy." (PMID 22307449, 2011). "Cardiocytes are less affected by dystrophin-deficiency than myofibers, however cardiocytes are generally incapable of regeneration leading to a late-stage cardiomyopathy." (PMID 19530190, 2009). "Thus, this review provides an in-depth analysis of the molecular mechanisms underlying dystrophin-deficient cardiomyopathy, including membrane instability, calcium dysregulation, mitochondrial dysfunction, and fibrosis." (PMID 41923738, 2026). "The loss of dystrophin, encoded by the DMD gene, is the main pathogenesis of DMD, resulting in progressively aggravated skeletal muscle weakness and atrophy, intellectual development disorders, and cardiomyopathy." (PMID 40236661, 2025). "In addition, muscle-related disorders were also addressed, with DMD (dystrophin) targeted in 6% of studies aiming to restore protein expression in Duchenne muscular dystrophy-associated cardiomyopathy." (PMID 40465697, 2025). "It has been hypothesised that in females with heterozygous DMD mutations the onset of cardiomyopathy may be associated with skewed XCI, as in skeletal muscle." (PMID 40035839, 2025). "There is a need for therapies specific to the loss of dystrophin and the subsequent pathophysiologic cascade that may differ from cardiomyopathy of other etiologies." (PMID 39268580, 2024). "This case may provide new insights into the pathogenesis, diagnosis, and management of DMD-associated cardiomyopathy complicated by acute myocarditis." (PMID 39290213, 2024). "These early hallmarks of the dystrophin-deficient cardiomyopathy can be helpful in evaluating and translating therapeutic effects of preclinical trials performed during the occult phase of the cardiomyopathy." (PMID 38637619, 2024). "It is hypothesized that sarcolemmal ion channel abnormalities may occur prior to the onset of cardiomyopathy in the dystrophic heart and may represent a primary effect of the DMD mutation." (PMID 39056750, 2024). "As patients age, recurrent episodic insults to dystrophin-deficient cardiac myocytes may strongly contribute to the progression of primary cardiomyopathy." (PMID 39290213, 2024). "Accordingly, in this study we investigated the hypothesis that dystrophin mutations in DMD lead to cardiomyopathy-causing bioenergetic/metabolic impairments, which could be therapeutically targeted to improve cardiac function." (PMID 36077200, 2022). "The female patient represented in this study suffered from a relative severe phenotype, characterized by skeletal myopathy and cardiomyopathy, which could be explained by a malignant mutation disrupting the N-terminal of the dystrophin gene." (PMID 35762211, 2022). "Mutations in the DMD gene disrupt the process of dystrophin protein production leading to a continuous decrease in muscular tension and power and resulting in loss of ambulation, respiratory failure and cardiomyopathy." (PMID 35010666, 2021). "As an X-linked gene, most female carriers of DMD mutations are asymptomatic although some may develop mild disease or cardiomyopathy, and it was unclear if the PPCM, in this case, was related to her carrier status." (PMID 33467574, 2021).
cardiomyopathy (continued). "A full-length human utrophin transgene expressed from a skeletal muscle-restricted promoter/enhancer (Tg(ACTA1-Utrn)2Ked; “Fiona”) was used to rescue the skeletal muscle pathology of dystrophin/utrophin-deficient mice (utrn–/– mdx; dko), allowing progression of cardiomyopathy (Fiona/dko)." (PMID 33651713, 2021). "In parallel, we present variations to current practices required to offset the identified shortfalls in iPSC-based models of dystrophin-associated cardiomyopathy which are similar to the “leagues” made by the sonnet’s speaker to satisfy both “heart’s and eye’s delight”." (PMID 32977524, 2020). "When crossed to the mdx dystrophin-deficient strain to produce the D2-mdx line of mice, this background significantly worsens mdx phenotypes, including an earlier onset of heart dysfunction and cardiomyopathy." (PMID 30745312, 2019). "As it is well established that cardiac abnormalities are lacking in these DMD/BMD mouse models, even in young adult animals, these Na+ channel defects in dystrophic neonatal cardiomyocytes can be considered primary effects of the dystrophin gene mutation, which precede cardiomyopathy development." (PMID 30360568, 2018). "Identifying the exosomal surface protein involved in initiating the cardioprotective effects may provide a novel target for the treatment of dystrophin-deficient cardiomyopathy." (PMID 30410044, 2018). "Furthermore, the presence of cardiomyopathy in 10–60% of carrier females (CFs), females carrying dystrophin gene mutations, known as symptomatic CFs, lends further weight to the necessity for changes in research approach." (PMID 30235804, 2018). "Approaches that can elicit expression of full-length utrophin, such as small drug treatment, in dystrophin-deficient hearts may have a clinically meaningful impact on the cardiomyopathy of DMD patients." (PMID 30417024, 2018). "Besides, loss of dystrophin has been linked with end-stage cardiomyopathies and has been proposed as a common pathway for contractile dysfunction in the failing myocardium and progression to HF." (PMID 29267303, 2017). "While AO exon skipping clinical trials appear promising for DMD17, 18, 20, 41, 42, the high incidence of cardiomyopathy in these patients, with associated high levels of mortality, indicate that restoring dystrophin protein in heart to modulate the cardiac phenotype is of high priority." (PMID 25758104, 2015). "Also, dystrophin loss has been related to end-stage cardiomyopathies and proposed as a common route for myocardial dysfunction and progression to advanced heart failure." (PMID 23935889, 2013). "Missense mutations or small deletions in some genes, for example, desmin (Des), integrin-linked protein kinase (Ilk), myosin regulatory light chain 2 (My12), dystrophin (Dmd), gelsolin (Gsn), lamin A/C (Lmna), and laminin subunit α-2 (Lama2), have been linked to cardiomyopathy." (PMID 23671862, 2013). "Previously, we demonstrated that a combined deficiency in dysferlin and dystrophin results in the development of a pronounced early-onset cardiomyopathy resembling that seen in DMD patients, in contrast to a mild, slowly progressing cardiac manifestation in mdx mice." (PMID 22132688, 2011). "Additionally, dystrophin deficiency markedly potentiates the unfavorable course of enterovirus induced cardiomyopathy." (PMID 20492678, 2010). "Previous study has showed that thesubendocardial dysfunction of left ventricular (LV) such as altered LV strainoccurred as early as in the age of 3 years and some variants in the DMD encodingthe cytoskeletal protein and dystrophin could cause a severe cardiomyopathy inthe early phase." (PMID 39228506, 2024). "The risk of developing cardiomyopathy increases with age, so cardiomyopathy is a potential problem that needs attention in female DMD variant carriers.Other study in MCs showed the incidence of cardiomyopathy was 7.3-16.7% and 0-13.3% for DMD and BMD, respectively." (PMID 38303044, 2024).